STAT3 (signal transducer and activator of transcription 3)
Diseases named in the same sentence as STAT3 in open-access papers (continued):
Sharing a sentence is not in itself a finding about the gene and the disease.
tumor (continued). "Also TLR9 expressing tumor cells lost the resistance to apoptosis by interfering with STAT3 signaling." (PMID 30233579, 2018). "Nonetheless, the 50% unresponsive mice group, presumably resistant to momelotinib treatment, that developed tumors showed levels of JAK2/STAT3 activation, c-Kit and Oct3/4 expression that were similar to their paclitaxel+ momelotinib counterparts in Phase 1 which also showed similar tumor burden." (PMID 29682172, 2018). "Suppression of STAT3 expression effectively reduces GBM tumor growth." (PMID 30551687, 2018). "Thus, it appears that the STAT3 functions in cancer can vary according to context, genetic background, and phase of the tumor." (PMID 30231582, 2018). "Furthermore, to test the role of the STAT3 pathway in tumour angiogenesis mediated by SIRT2, we collected CM from each group." (PMID 30584257, 2018). "Finally, STAT3 expression is increased and plays an important role in tumor-mediated immunosuppression." (PMID 29626935, 2018). "Importantly, Ponatinib significantly reduced STAT3 phosphorylation in tumor tissue after a single dose of 30 mg/kg compared to vehicle control." (PMID 30572654, 2018). "We then measured the levels of STAT3 in lysates prepared from tumor specimens." (PMID 30577812, 2018). "As STAT3 dysregulation contributes to many pathological situations during infectious or neoplastic diseases a broader understanding of miRNAs–STAT3 interactions could help to manipulate them for developing novel therapeutic approaches." (PMID 29967604, 2018). "There are a few reports that claim toll-like receptors (TLRs) could also activate STAT3, which is one of the pathways for this family of receptors to play a role in tumor development; however, their involvement is contentious." (PMID 30109213, 2018). "Moreover, abrogation of STAT3 signalling has also exhibited tumor growth impairment and induction of apoptosis in preclinical models." (PMID 30217007, 2018). "Recent studies have clarified that STAT3 regulates the expression of PD-L1 in antigen-presenting cells as well as in a number of tumor cells, including lung cancer and melanoma, to inhibit the tumor immune response." (PMID 30176876, 2018). "Among tumor-associated immune cells, tumor-associated macrophages were found to promote CSC-like phenotypes through Milk Fat Globule-EGF Factor 8 (MGF-E8)/STAT3 and Sonic Hedgehog pathways, or through EGFR/STAT3/Sox2." (PMID 29588647, 2018). "In addition, since STAT3 has been found to play crucial roles in magnitude of tumor mediated immunosuppression and immune escape in tumor microenvironment, miRNA-based immunotherapy targeting on STAT3 should be aggressively pursued." (PMID 30046565, 2018). "Since the IFN-response pathway can inhibit tumorigenesis through indirect effects on the tumor microenvironment, we propose that high STAT3 levels in GICs may inhibit these IFN-response genes and promote GBM tumorigenesis." (PMID 29774125, 2018). "Efforts to identify specific signaling motifs of the short intracytoplasmic sequence of PD-L1 revealed regulatory non-classical signal transduction motifs that counteract and confer resistance to IFN-β-mediated cytotoxic signals, protecting tumor cells from apoptosis by the STAT3–Caspase-7 axis." (PMID 30123774, 2018). "Indeed, STAT3 transcriptional functions are required for tumor transformation by oncogenes that trigger its YP, such as, for example, Src." (PMID 30231582, 2018). "Thus, the evidence suggested that the suppression of tumor metastasis by antrodan was related to the modulation of the IL-6/STAT-3 pathway." (PMID 29794990, 2018). "Indeed, STAT3 phosphorylation increases expression of HIF1α by inhibiting HIF1α degradation in tumor cells." (PMID 29518129, 2018). "The hypothesis that the STAT3/Slug signal enhances cancer stem-like properties and tumor-initiating ability in GBM cells was tested in the following experiments." (PMID 30551687, 2018).
tumor (continued). "Curcumin is able to exert anti-tumor action through inhibiting the STAT3 signaling pathway." (PMID 30518397, 2018). "Previous studies reported that S1PR1, one of five G protein-coupled receptors for S1P, could maintain persistent STAT3 activation in tumorigenesis and is essential for tumor metastasis and angiogenesis." (PMID 30377291, 2018). "Thus, it can be inferred that STAT3 activity in 4T1 cells, and potentially also within the tumour microenvironment, is likely critical to the invasive and metastatic phenotype of 4T1 cells." (PMID 29875329, 2018). "However, aberrant STAT3 activation leads to cancer cell proliferation, survival and resistance to apoptosis, thereby accelerating tumor development and progression." (PMID 29686295, 2018). "However, in cancers, including breast, ovarian and prostate, STAT3 is constitutively active in certain populations of tumor cells." (PMID 29682172, 2018). "In addition, aberrant STAT3 activation in HNSCC contributes to tumor growth and resistance to standard therapies." (PMID 29545751, 2018). "Importantly, constitutive STAT3 activation has been documented in several tumor types and is correlated with tumorigenesis." (PMID 30186159, 2018). "Finally, STAT3 activity is also crucial to determine the pro-tumorigenic features of most tumor stromal cells." (PMID 30231582, 2018). "Previous studies found that MAPK played a direct inhibitory modification on Stat3 in tumour cells." (PMID 29662665, 2018). "PIAS3 is an endogenous inhibitor of STAT3 through prohibiting its DNA binding, and the loss of PIAS3 in cancers contributes to enhanced STAT3 activity and subsequent tumor growth, as well as impacts patient survival, identifying PIAS3 a promising therapeutic target." (PMID 29950561, 2018). "Primarily, IL-6 activates signal transducer and activator of transcription 3 (STAT3) signaling thus promotes tumor cell proliferation and enhances cell invasiveness in cancers, which is in line with the constitutive activation of STAT3 in RCC, especially in metastatic disease." (PMID 29717134, 2018). "To confirm whether the down-regulation of Stat3 leads to tumour growth inhibition, we performed Fluc imaging to detect the tumour growth in vivo." (PMID 30297887, 2018). "Activated STAT3 contributes to tumor progression, as well as resistance to treatment." (PMID 29652858, 2018). "In addition, we found that 17-AAG had a combined effect in the downregulation of HDAC1, HDAC2, the anti-apoptotic gene BCL-2 and tumour survival gene STAT3 in Hep3B cells in combination with Resminostat." (PMID 30035186, 2018). "Moreover, IATL treatment increased the expression of CHOP in the mRNA and protein levels, and decreased the protein expression levels of p-STAT3 and STAT3 in tumor tissues." (PMID 30541589, 2018). "Phosphorylated STAT3 protein can translocate into the nucleus, bind to DNA, and activate the transcription of various genes that regulate vital cellular functions, including cell survival, proliferation, angiogenesis, and tumor evasion." (PMID 29849942, 2018). "Besides tumor vascularization, STAT3 activity in TAMs seems to promote tumorigenesis and therapeutic resistance by nurturing a population of cancer cells with increased tumorigenic potential, known as cancer stem/initiating cells." (PMID 29921770, 2018). "IL-6 (Interleukin-6) and GP130 are part of the IL-6/JAK/STAT3 pathway that is involved in proliferation, survival, invasiveness and metastasis of tumor cells and in suppression of the anticancer immune response, and constitutes an attractive target for anti-cancer therapies." (PMID 30190791, 2018). "While this finding needs further evaluation, it might be that IL-6/leptin-induced STAT3 is required earlier in DEN-induced HCC e.g. in tumor initiation or during progression." (PMID 30224299, 2018).
tumor (continued). "In this work, however, we will only briefly describe details of STAT3 modulation and functions in normal and neoplastic cells or its crucial and pleiotropic roles in the tumor microenvironment, since these topics are very well and exhaustively reviewed by very recent works." (PMID 30231553, 2018). "Bioluminescence imaging of Rluc was performed to assess Stat3 activation in the tumours." (PMID 30297887, 2018). "STAT1 and STAT3 activation is reciprocally regulated and the components appear to play opposite roles in proliferation, apoptotic death, inflammatory and anti-tumor immune responses: STAT1 is considered to be a tumor-suppressor gene, while STAT3 is regarded as an oncogene." (PMID 29894486, 2018). "Moreover, PIAS3 functioned to negatively regulate cell growth and tumor sphere formation in GBM cells, indicating that PIAS3 loss in GBM contributes to enhanced STAT3 activity and subsequent cell proliferation." (PMID 29950561, 2018). "Blocking STAT3 expression in conditional knockout mice or STAT3 inhibitors could markedly reduce the expansion of MDSCs and increase T-cell responses in tumor-bearing mice." (PMID 29765990, 2018). "Furthermore, sources suggest that the constitutive phosphorylation of STAT3 at serine 727 is detected in various types of human malignancies and is essential for tumor cell growth and invasion." (PMID 30286779, 2018). "However, inhibition of HGF expression in CAFs and STAT3 in MGC803 cells significantly decreased tumor growth." (PMID 30158543, 2018). "The increased leptin could bind to LepR and activate Jak2/STAT3 signaling in BMSCs, thus forming more BMAs and creating a positive feedback for tumor cells." (PMID 30013512, 2018). "Our recent studies have revealed that IL-32α induced TNFR1-mediated cell death signaling to inhibit tumor development in carcinogen-induced colon tumors, while IL-32β and IL-32γ suppressed tumor growth through the inactivation of STAT3 and NF-κB signaling in xenograft and allograft animal." (PMID 30486830, 2018). "STAT3 signaling pathway plays critical roles in tumor invasion and metastasis." (PMID 29717134, 2018). "Knockdown and overexpression studies showed that OCIAD2 is essential for STAT3 activation and cell migration, which could contribute to its role in tumor metastasis." (PMID 29743632, 2018). "Significant STAT3 activation was also observed in the tumor stroma in our study." (PMID 29963254, 2018). "In addition, inflammation activates the signal transducer and activator of transcription 3 (STAT3) and β-catenin signaling pathways, which induce proliferation and remodeling of epithelial cells and then promote tumor development." (PMID 30510778, 2018). "We were interested in exploring whether STAT3 was involved in tumour angiogenesis mediated by SIRT2 in CRC, so we conducted related experiments." (PMID 30584257, 2018). "The NF-κB-dependent tumor growth factor released by IECs could be IL-6, which plays an important role in proliferation and can activates STAT3." (PMID 29464031, 2018). "Aberrant JAK2/STAT3 signaling has been detected in a variety of tumor types, indicating that STAT3 inhibitors might to be widely effective as anticancer therapies." (PMID 30154439, 2018). "Moreover, STAT3 is a critical transcription activator biomarker in tumor therapy and is also involved in a series of fundamental events implicated in the development of tumors." (PMID 30123088, 2018). "It has been reported that knockdown of STAT3 protein in 4T1 cell line by small interfering RNA (siRNA) reduce expression of c-Myc and completely block expresion of Twist protein, thus inhibiting tumor growth and metastasis." (PMID 29963272, 2018). "It was reported that nearly 60% of clinical HCC tumor samples showed nuclear phosphorylated-STAT3 staining, suggesting that targeting STAT3 signaling pathway may be an effective treatment for HCC with constitutively or inductively active STAT3." (PMID 29558404, 2018).
tumor (continued). "Furthermore, miR-197/CKS1B/STAT3-mediated network regarded the tumor expression of PD-L1 as a biomarker of this cascade, and the biological interaction between PD-L1 and chemoresistance occurred through this microRNA regulatory cascade." (PMID 30290817, 2018). "The JAK2/STAT3 signaling pathway is closely related to tumor development." (PMID 30271456, 2018). "Although, recent reports implied that niclosamide inhibits tumor growth through suppressing Wnt, Notch, mTOR and STAT3 pathways, its exact antitumor mechanism remains unclear." (PMID 30258081, 2018). "Recent works also discovered that several G-protein-coupled receptors (GPCRs) and Toll-like receptors (TLRs), such as TLR9 and TLR4, can activate STAT3 pathway that, in turn, upregulating the expression of certain TLRs in transformed cells, promotes tumor progression." (PMID 30231553, 2018). "Taken together, CK inhibited tumor growth and induced apoptosis in vivo, activities that might be related to regulating STAT3 and ERS in HCC cells." (PMID 29921768, 2018). "Moreover, STAT3-mediated aerobic glycolysis contributes to the ability of constitutively active STAT3 to act as a hit in tumor transformation." (PMID 30231582, 2018). "Importantly, a series of rescue experiments suggested that the function of SIRT2 in tumour angiogenesis depends on the STAT3/VEGFA signalling pathway." (PMID 30584257, 2018). "Importantly, GBM-R2I2 xenograft tumor specimens had higher STAT3 expression than GBM-Par specimens based on Q-PCR analysis." (PMID 30551687, 2018). "However, considerable evidence has demonstrated that EGFR blockade, or inhibition of other receptor systems such as HER2, MET and IGF-IR leads to enhanced or re-activated STAT3 activity and subsequent continued tumor progression." (PMID 30572654, 2018). "Therefore, up-regulation of HAGLROS in GC is partly due to STAT3 activation during tumor progression." (PMID 29329543, 2018). "Similarly, they found that p-STAT3 overexpression is related to tumor differentiation and lymph node metastases." (PMID 29560131, 2018). "Results showed that phosphorylation of STAT3 in SGC-7901 tumor was suppressed by ICTS." (PMID 29915371, 2018). "Recent research has shown that currently available chemotherapeutic drugs for NSCLC induce STAT3 activation, suggesting that STAT3 may play an important role in tumor resistance to prevailing chemotherapy in NSCLC." (PMID 29576846, 2018). "Furthermore, our data revealed increased expression of interferon gamma (Ifng) and granzyme B (Gzmb) in female LR/Stat3Δ/Δ mice, suggesting anti-tumor immune responses in Stat3-deleted females." (PMID 30389925, 2018). "STAT3 is classed as an oncogene and plays a pivotal role in carcinogenesis and tumour formation." (PMID 29301334, 2018). "However, different administration protocols with the same total dose of STAT3 siRNA exert the similar inhibition effects on tumor development." (PMID 29348670, 2018). "However, STAT3 has also been shown to act as a tumor suppressor in a number of cases, suggesting that its activity is strongly context-specific." (PMID 30231582, 2018). "The IL-6/STAT3 pathway has been proved to be a crucial tumor promoter in CAC." (PMID 30498394, 2018). "PARK2 can inhibit the JAK2/STAT3/VEGF signaling pathway, and also through association with other genes and protein–protein interactions, regulate the network of growth pathways, thus becoming a vital tumor suppressor." (PMID 29515107, 2018). "However, much evidence indicates that STAT3 is constitutively activated in cancers, playing a crucial role in tumor onset and progression." (PMID 29329543, 2018). "STAT3 activation in the context of HCV infection has also been linked to the presence of myeloid-derived suppressor cells (MDSCs), a cell type that favors the expansion of Treg lymphocytes and has been associated with an increased tumor burden in HCC patients." (PMID 30279347, 2018). "Stat3 plays an important role in regulating inflammation and tumor progression." (PMID 29762501, 2018).
tumor (continued). "Stat1, STAT2, STAT3 and Tbet mRNA expression were tendencially upregulated in total lungs cells derived from αPD-1 antibody- treated tumor bearing mice independent from in vitro re-challenge." (PMID 30647851, 2018). "For that, STAT3 is widely considered as an oncogene and an attractive therapeutic target, although recent evidence have proved its ability to suppress malignant cell onset and/or progression in particular tumor backgrounds." (PMID 29914167, 2018). "On the other hand, c-PARP was evidently activated in two distinct tumor tissues after treatment with CsA/Gef-NPs, indicating that the inhibition of STAT3 by CsA augmented the Gef-induced apoptosis of tumor cells, a finding that is consistent with the observed potent suppression of tumor growth." (PMID 29942660, 2018). "STAT3 is constitutively activated in both tumor and immune cells by IL-6." (PMID 29419779, 2018). "For example, MFG-E8 secreted by tumor-associated macrophages maintains self-renewal of colorectal CSCs through the STAT3/Sonic Hedgehog signaling pathway; knockdown of MFG-E8 in the tumor-associated macrophages significantly inhibited tumorigenicity of CSCs in immunodeficient mice." (PMID 30279970, 2018). "IL-6/STAT3 is the main pathway through which IL-6 regulates tumor-promoting activities." (PMID 29930760, 2018). "Additionally, GPRC5A knockout enhances the transformed phenotype in normal and tumor cells through the aberrant activation of the EGFR/STAT3 signaling pathway." (PMID 30417009, 2018). "Among them, STAT3 has been shown to play a prominent role in tumor growth and invasion." (PMID 30091994, 2018). "In vivo information from murine models of TN-BC showed different response to STAT3 pathway blocking in vitro vs in vivo (i.e. IL-6 pathway inhibition did not influence tumour cell proliferation in vitro but potently reduced tumour growth using TN models of murine BC in vivo)." (PMID 29256156, 2018). "In addition, we uncover efficacy mechanisms including inhibition of tumor cell proliferation, apoptosis induction, inhibition of p‐Stat3/PD‐L1 pathway." (PMID 29733528, 2018). "In addition, STAT3 has been reported to act as an oncogenic factor to promote tumor growth in liver tumorigenesis." (PMID 29729074, 2018). "Canonical NF-κB also modifies the tumor microenvironment by inducing the secretion of proinflammatory cytokines such as IL-6, resulting in the activation of its responsive transcription factor STAT3 in K-Ras-mutant lung tumors." (PMID 29601548, 2018). "We observed that there was significant upregulation of phosphorylated STAT3 (pSTAT3) in tumor‐driven like macrophages than hTERT‐HPNE‐CM‐treated or parent THP‐1 monocytes, and we also found that hTERT‐HPNE‐CM upregulated pSTAT3 level in THP‐1 monocytes slightly." (PMID 30311406, 2018). "Similar to current results, nuclear expression of phosphorylated STAT3 (p-STAT3, the activated form of STAT3) has also been recently shown to be associated with small tumour size, low grade and negative LVI and to be a positive prognosticator of BCSS." (PMID 29256156, 2018). "Furthermore, garcinol also mediated anti-tumor effect by inhibiting the constitutive activation of STAT3 and NF-κB in squamous cell carcinoma of the head and neck." (PMID 29370858, 2018). "In addition, IL-6 can induce the expression of G3BP1, while G3BP1 depletion diminishes the IL-6-elicited STAT3 activation and leads to inhibition of tumor cell growth and invasion in RCC." (PMID 29717134, 2018). "We further explored whether the STAT3/Slug transcriptional axis mediated the tumor-initiating capability and CSC properties of GBM-R2I2 cells." (PMID 30551687, 2018). "Additionally, activation of AKT and STAT3 plays an essential role in tumour development and progression." (PMID 29416013, 2018).